PPFIA4 (PPFI scaffold protein A4)
Description:
May regulate the disassembly of focal adhesions. May localize receptor-like tyrosine phosphatases type 2A at specific sites on the plasma membrane, possibly regulating their interaction with the extracellular environment and their association with substrates (By similarity).
Tractability: Antibody: UniProt places it where antibodies can reach, with medium confidence. PROTAC: ubiquitination databases record sites on it; its protein half-life has been measured.
Gene: Protein-coding gene on chromosome 1 (203,026,491 to 203,078,740, forward strand). Ensembl gene ENSG00000143847.
Subcellular location: Cytoplasm; Cell surface
Pathways (Reactome):
Neuronal System: Acetylcholine Neurotransmitter Release Cycle; Dopamine Neurotransmitter Release Cycle; Glutamate Neurotransmitter Release Cycle; Norepinephrine Neurotransmitter Release Cycle; Receptor-type tyrosine-protein phosphatases; Serotonin Neurotransmitter Release Cycle
Gene Ontology:
Molecular function: protein binding
Biological process: synapse organization
Cellular component: cytosol; presynaptic active zone; synapse; cell surface; cytoplasm
Genetic constraint (gnomAD): Loss-of-function variants: 97 observed, 125.3 expected, observed/expected ratio (o/e) 0.77, 90% interval 0.66 to 0.92. The upper end of that interval is the gene's LOEUF score, 0.92, which puts it in group 3 of 6, group 1 being the genes least tolerant of losing a copy. Missense variants: 1,442 observed, 1,505.7 expected, observed/expected ratio (o/e) 0.96, 90% interval 0.92 to 1. Synonymous variants: 625 observed, 591.31 expected, observed/expected ratio (o/e) 1.06, 90% interval 0.99 to 1.13.
Homologues: Orthologues: macaque PPFIA4 (98% identical), chimpanzee PPFIA4 (98% identical), guinea pig PPFIA4 (94% identical), dog PPFIA4 (94% identical), pig PPFIA4 (94% identical), mouse Ppfia4 (93% identical), rat Ppfia4 (93% identical), rabbit PPFIA4 (92% identical), zebrafish ppfia4 (72% identical), Drosophila melanogaster Liprin-alpha (51% identical). Paralogues in human: PPFIA2 (70% identical), PPFIA1 (66% identical), PPFIA3 (60% identical), PPFIBP1 (20% identical), PPFIBP2 (18% identical).
Diseases named in the same sentence as PPFIA4 in open-access papers:
PPFIA4 is named in the same sentence as 31 diseases in open-access papers, as found by Europe PMC text mining. Sharing a sentence is not in itself a finding about the gene and the disease. The quoted sentences say what the papers report.
colon cancer (6 papers, 2021 to 2024). "High expression of PPFIA4 is associated with poor prognosis in colon cancer patients and promotes cancer cell metastasis by enhancing tumor glycolysis." (PMID 36338972, 2022). "Findings of this study potentiated the use of PPFIA4 as a candidate diagnostic and therapeutic marker for colon cancer." (PMID 34094943, 2021). "In our study, our TCGA analysis for the first time showed that PPFIA4 upregulation is a hallmark not limited to colon cancer, and a broad range of cancers are characterized by PPFIA4 upregulation." (PMID 34094943, 2021). "Our bioinformatics analysis identified PPFIA4 as a potential diagnostic and therapeutic biomarker in colon cancer." (PMID 34094943, 2021). "Since currently available studies have implied the relationship between PPFIA4 and metabolism regulation, an important part of the present study was to evaluate if PPFIA4 upregulation was linked to glycolysis of colon cancer." (PMID 34094943, 2021). "Up-regulation of the PPFIA4 is correlated with higher clinical stages and poor survival of colon cancer patients." (PMID 38360831, 2024). "PPFIA4 is a cellular oncogene that is involved in promoting the proliferation and migration of various cancer cells, including colon cancer." (PMID 38360831, 2024). "MYOD1 is a transcription factor that plays a key role in the differentiation of skeletal muscle tissue, while PPFIA4 are genes that are involved in prostate and colon cancer progression." (PMID 36672609, 2022). "For instance, PPFIA4 has been shown to promote colon cancer cell proliferation and migration by enhancing tumour glycolysis." (PMID 36317123, 2022). "Proliferation and migration of tumor cells in colon cancer are facilitated by PPFIA4’s ability to increase tumor glycolysis; PPFIA4 also increases mitochondrial metabolism via MTHFD2 in desmoplastic-resistant prostate cancer." (PMID 35924146, 2022). "Consistently, HCT116, which is a well-known aggressive colon cancer cell line, demonstrated the highest PPFIA4 expression." (PMID 34094943, 2021). "Higher promoter methylation levels of PPFIA4 were also found to be in the primary colon tumor than normal tissues." (PMID 34094943, 2021). "Our data support the potential use of PPFIA4 silencing as another tool for reprogramming the energetic metabolism of colon cancer." (PMID 34094943, 2021). "PPFIA4 upregulation is a potential biomarker in colon cancer which promotes proliferation, migration, invasion and glycolysis." (PMID 34094943, 2021). "It was found that colon cancer patients with higher expression of PPFIA4 had poorer OS rate (p<0.05)." (PMID 34094943, 2021). "Here we showed that overexpression and silencing of PPFIA4 resulted in increased and decreased glycolysis of colon cancer, respectively." (PMID 34094943, 2021). "PPFIA4 expression is essential for colon cancer cell proliferation, migration, invasion and glycolysis." (PMID 34094943, 2021). "PPFIA4 upregulation also correlated with poor prognosis and higher clinical stages of colon cancer patients." (PMID 34094943, 2021). "As cancer is characteristic of dysregulated metabolism and cancer cells rely on glycolysis for enhanced energy production, we next evaluated the effect of PPFIA4 on colon cancer metabolism." (PMID 34094943, 2021). "Here we aimed to characterize the PPFIA4 gene, as a glycolysis-related oncogene in promoting the proliferation and migration of colon cancer cells." (PMID 34094943, 2021). "Next, we investigated the specific mechanism by which PPFIA4 promoted the proliferation, migration, invasion and glycolysis of colon cancer cells." (PMID 34094943, 2021). "Furthermore, treating colon cancer cells with Ag@Gln-TSC NPs caused significant down-regulation of the HULC Lnc-RNA and PPFIA4 oncogene by 0.3 and 0.6 folds, respectively." (PMID 38360831, 2024).
colon cancer (continued). "We validated that PPFIA4 was highly correlated with the survival and prognosis of colon cancer patients, and this study focused on evaluating the role of PPFIA4 in promoting proliferation, migration and invasion of colon cancer cells." (PMID 34094943, 2021). "Using bioinformatical tools including The Cancer Genome Atlas (TCGA) and Gene Expression Profiling Interactive Analysis (GEPIA), we found that PPFIA4 expression and methylation levels were higher in colon cancer tissues of different stages than in normal tissues." (PMID 34094943, 2021). "Our study reports PPFIA4 as a potential novel therapeutic target in colon cancer." (PMID 34094943, 2021). "Colon cancer cell viability, migration and migration were enhanced after PPFIA4 overexpression." (PMID 34094943, 2021). "We used qRT-PCR to detect the expression of PPFIA4 in colon cancer cell lines, and found that the level of PPFIA4 was higher in colon cancer cells, including SW403, HT29, CAco-2, DLD1, SW480, HCT116, and COLO320, than that in normal colon cell lines, including NCM460 and CCD-18Co." (PMID 34094943, 2021). "We next explored the role of PPFIA4 in colon cancer cell migration and invasion." (PMID 34094943, 2021). "PPFIA4 silencing could be a strategy for reprogramming glycolysis of colon cancer, and its efficacy is dependent on ENO2/PFKFB3." (PMID 34094943, 2021). "The correlation between PPFIA4 and phenotypes of colon cancer was also validated through ectopic overexpression of PPFIA4 in SW403 cells and silencing of PPFIA4 in HCT116 cells, which led to enhanced and suppressed cell proliferation, migration and invasion, respectively." (PMID 34094943, 2021). "We confirmed that all colon cancer cell lines showed upregulated PPFIA4 at different degrees." (PMID 34094943, 2021). "This indicated that PPFIA4 could promote the glycolysis process in colon cancer cells." (PMID 34094943, 2021). "Our work indicated that PPFIA4 was significantly down-regulated by Ag@Gln-TSC NPs, indicating their potential to inhibit the proliferation of colon cancer cells." (PMID 38360831, 2024). "We first analyzed the correlation between PPFIA4 and two glycolysis-related genes, ENO2 (enolase 2) and PFKFB3 (6-Phosphofructo-2-Kinase/Fructose-2,6-Biphosphatase 3), in the TCGA colon cancer database." (PMID 34094943, 2021). "The positive correlation between PPFIA4 and ENO2/PFKFB3 levels also corroborated that PPFIA4 was a potential regulator of glycolysis in colon cancer." (PMID 34094943, 2021). "Notably, the SW403 cell line, which was previously shown to be relatively less aggressive and non-metastatic, showed the lowest level of PPFIA4 upregulation among all colon cancer cell lines investigated in our study." (PMID 34094943, 2021). "No study has suggested a link between PPFIA4 and colon cancer." (PMID 34094943, 2021).
colorectal cancer (5 papers, 2021 to 2025). A primary or metastatic malignant neoplasm that affects the colon or rectum. "PPFIA4 encodes the protein liprin-α4, which has been implicated in promoting tumor glycolysis and angiogenesis via Wnt signaling, and may contribute to colorectal cancer progression through immune modulation." (PMID 40991561, 2025). "Collectively, these findings indicate that PPFIA4 plays a key role in colorectal cancer cell proliferation and migration, making it a potential therapeutic target." (PMID 40991561, 2025). "We further analyzed the survival of PPFIA4 in colorectal cancer patients on the GEPIA website and found that colorectal cancer patients with higher expression of PPFIA4 showed poorer OS (p=0.00024) and recurrence-free survival (p=0.00016)." (PMID 34094943, 2021). "In addition, the up-expressions of SAP30 and PPFIA4 were also, respectively, verified in a bioinformatics study of hepatocellular carcinoma and an experimental study of colorectal carcinoma." (PMID 36362375, 2022). "Overexpression of PPFIA4 could increase the expression of EMT-related proteins and promote the proliferation, migration and invasion of colorectal cancer cells." (PMID 36605492, 2023).
prostate carcinoma (5 papers, 2022 to 2023). A carcinoma that arises from epithelial cells of the prostate gland. "Additionally, PPFIA4 expression was significantly increased in castration-resistant prostate cancer tissues compared to that in prostate cancer." (PMID 36605492, 2023). "Besides, previous studies suggested that PPFIA4 was also the key prognostic gene in thyroid and prostate cancer." (PMID 35734431, 2022).
breast carcinoma (2 papers, 2023). "The PPFIA4 gene was shown to be upregulated in response to hypoxia (through HIF1) in all types of breast cancer cell lines and normal-like epithelial cells, including MCF10A83." (PMID 37414767, 2023).
clear cell renal cell cancer (2 papers, 2022 to 2023). "There is emerging evidence indicating that PPFIA4 plays an important role in several malignancies including refractory pancreatic cancer, small cell lung cancer, and clear cell renal cell cancer." (PMID 35382861, 2022).
epilepsy (2 papers, 2022 to 2023). A brain disorder characterized by episodes of abnormally increased neuronal discharge resulting in transient episodes of sensory or motor neurological dysfunction, or psychic dysfunction. "A total of seven hub genes were identified in BY chickens, among which PPFIA4 is a prognostic monitoring indicator of thyroid cancer, lipoma and epilepsy, and DYTN is associated with Leiber visual atrophy, dystonia and lymphatic malformations." (PMID 36557693, 2022).
pancreatic cancer (2 papers, 2021 to 2022). "PPFIA4 belongs to the liprin-alpha gene family and inhibition of PPFIA4 reduced pancreatic cancer cell proliferation and invasion." (PMID 33954109, 2021).
asthma (1 paper, 2022). "The exact mechanisms underlying the observed relationship of genetic loci and metabolites—e.g., genes within chromosome 1q32 (e.g., ADORA1, PPFIA4) and sphingomyelin (d17:1/16:0, d18:1/15:0, d16:1/17:0)—with asthma risk warrant further clarification." (PMID 36818476, 2022). "Studies have shown that genes on chromosome 1q32, including ADORA1 and PPFIA4 are associated with asthma risk, and ADORA1 may interact with sphingolipids to enhance airway inflammation." (PMID 36818476, 2022).
atrial fibrillation (1 paper, 2023). A disorder characterized by an electrocardiographic finding of a supraventricular arrhythmia characterized by the replacement of consistent P waves by rapid oscillations or fibrillatory waves that vary in size, shape and timing and are accompanied by an irregular ventricular response. "A previous study discovered that variants of PPFIA4 were associated with supernormal coronary arteries and atrial fibrillation." (PMID 37637145, 2023).
cholangiocarcinoma (1 paper, 2022). A carcinoma that arises from the intrahepatic biliary tree (intrahepatic cholangiocarcinoma) or from the junction, or adjacent to the junction, of the right and left hepatic ducts (hilar cholangiocarcinoma). "In addition, we investigated PPFIA4 expression in a cohort of patient with cholangiocarcinoma samples from our hospital by IHC assay, which demonstrated predominant expression of PPFIA4 within tumor cells." (PMID 35924146, 2022). "When compared to non-tumor tissues, the amount of PPFIA4 mRNA in cholangiocarcinoma tissues became much higher." (PMID 35924146, 2022).
gastritis (1 paper, 2026). Inflammation of the stomach. "Human gastric PPFIA4 correlated with H. pylori colonization and the severity of gastritis, and H. pylori colonization and inflammation were attenuated in Ppfia4ΔGEC mice." (PMID 42065246, 2026). "Overall, PPFIA4 could be a promising therapeutic target, as it collectively ensures H. pylori persistence and promotes gastritis." (PMID 42065246, 2026).
hepatocellular carcinoma (1 paper, 2022). A malignant tumor that arises from hepatocytes. "In this study, we first proposed that the abnormally high expressions of ENO2 and PPFIA4 was related to the poor prognosis of hepatocellular carcinoma, though they had been experimentally reported in other cancers." (PMID 36362375, 2022). "Among the ceRNA network, six highly expressed lncRNAs (AC005540.1, AC012146.1, AC073529.1, AC090772.3, AC138150.2, AL390728.6) and one highly expressed mRNA (PPFIA4) were the potential biomarkers of hepatocellular carcinoma which we firstly reported." (PMID 36362375, 2022). "We obtained a prognostic signature including eight hypoxia genes (ENO2, KDELR3, PFKP, SLC2A1, PGF, PPFIA4, SAP30, and TKTL1) and further established a hypoxia-related prognostic ceRNA network including 17 lncRNAs, six miRNAs, and seven mRNAs for hepatocellular carcinoma." (PMID 36362375, 2022).
Hypertension (1 paper, 2024). The presence of chronic increased pressure in the systemic arterial system. "Two of the recurrent AF genes also code for functions directly or indirectly linked to AF (CASQ2 and GOSR2), and some genes indicate a possible indirect link related to comorbidities, e.g., hypertension or malignancy (PPFIA4, USP34, WIPF1, SPATS2L, CAND2, and AOPEP)." (PMID 38725839, 2024).
myocardial infarction (1 paper, 2023). Gross necrosis of the myocardium, as a result of interruption of the blood supply to the area, as in coronary thrombosis. "Of the 4 hub genes, ADM was upregulated in CAD (GSE56885), PPFIA4 and TPBG were upregulated in patients with ischemic heart disease (GSE48166), and FAM162A was downregulated in patients with myocardial infarction (GSE141512)." (PMID 37637145, 2023).
nodular goiter (1 paper, 2021). Goiter characterized by discrete tissue mass(es) that may or may not produce thyroid hormones. "CHST6, FBP2, PPFIA4, and TGFBI proteins were all upregulated in THCA tissues compared with nodular goiter tissues." (PMID 33981593, 2021).
prostate adenocarcinoma (1 paper, 2021). "Another study identified five glycolysis-related mRNAs (GYS2, STMN1, PPFIA4, KDELR3, and ABCB6) which were associated with patients experience biochemical recurrence (BCR) after radical prostatectomy (RP) in patients with prostate adenocarcinoma." (PMID 34489401, 2021).
sarcoma (1 paper, 2022). A usually aggressive malignant neoplasm of the soft tissue or bone. "The sarcoma and LUAD signatures had three common genes (PPFIA4, BNIP3L, NDRG1)." (PMID 35079065, 2022).
tumor (11 papers, 2021 to 2025). "After ruling out LEP as a potential biomarker using TCGA analysis, we found that higher PPFIA4 levels were associated with primary tumor, higher stage (II-IV), and higher N stage (referring to a higher number of lymph node metastasis adjacent to tumor in the TNM staging system)." (PMID 34094943, 2021). "In contrast, PPFIA4 depletion in C4-2B xenografts grown in castrated nude mice resulted in delayed tumor progression, with the mean tumor volume at 620±105.2 mm3 in C4–2B-shPPFIA4 xenografts but 1363±268.5mm3 in the control group." (PMID 35382861, 2022). "In our risk score model, three hub genes, including PPFIA4, SERPINE1, and STC2, were all identified to be differentially expressed between normal and tumor tissues and be closely associated with the prognosis and infiltration of immune cells in CC patients." (PMID 35734431, 2022). "We confirmed the high expression of PPFIA4 in the tumor tissues of CHOL patients through fresh tumor tissues and their corresponding paraneoplastic tissue and previous pathological slides collected clinically." (PMID 35924146, 2022). "Overexpression of PPFIA4 promotes tumor progression and reduces the overall survival of patients with CRC." (PMID 36465397, 2022). "PTPRF Interacting Protein Alpha 4 (PPFIA4) was reported to be glycolysis-associated signature, involved in glycolysis of tumor microenvironment." (PMID 35924146, 2022). "Sh-PPFIA4 suppressed proliferation and migration, while it accelerated apoptosis of tumor cells." (PMID 36226248, 2022). "LncRNA MNX1-AS1/PPFIA4 accelerates tumor growth in COAD model." (PMID 36226248, 2022). "We hypothesized that the expression status of PPFIA4 in CHOL tumor tissues could reflect the hypoxic status in tumor tissues." (PMID 35924146, 2022). "When castrated mice carrying LNCaP or VCaP xenografts (vector and PPFIA4) were treated with DS18561882, the inducible effects of PPFIA4 on tumor growth could hardly be detected, as evidenced by tumor growth, tumor volume, and the proliferation index Ki67." (PMID 35382861, 2022). "Our in vitro experiments demonstrated that PPFIA4 knockdown significantly inhibited CRC cell proliferation and migration, supporting its functional relevance in tumor progression." (PMID 40991561, 2025). "We investigate the expression of the protein tyrosine phosphatase receptor type F polypeptide interacting protein alpha 4 (PPFIA4) using public datasets and tumor specimens from PCa cases by immunohistochemistry." (PMID 35382861, 2022).